RNU7-192P (RNA, U7 small nuclear 192 pseudogene)
Gene: Small nuclear RNA gene on chromosome 4 (188,716,665 to 188,716,725, reverse strand). Ensembl gene ENSG00000252275.
Homologues: Orthologues: chimpanzee U7 (98% identical), macaque U7 (92% identical). Paralogues in human: RNU7-57P (84% identical), RNU7-67P (84% identical), RNU7-80P (80% identical), U7 (80% identical), RNU7-11P (79% identical), RNU7-124P (79% identical), RNU7-171P (79% identical), RNU7-52P (79% identical), RNU7-60P (79% identical), U7 (79% identical), RNU7-13P (77% identical), RNU7-154P (77% identical), and 142 more.